PPIL4 (peptidylprolyl isomerase like 4)
Description:
PPIases accelerate the folding of proteins. It catalyzes the cis-trans isomerization of proline imidic peptide bonds in oligopeptides (By similarity).
Synonyms: HDCME13P
Tractability: Small molecule: a structure with a bound ligand is known. PROTAC: UniProt records ubiquitination sites on it; ubiquitination databases record sites on it; its protein half-life has been measured.
Target class: Isomerase; Enzyme
Gene: Protein-coding gene on chromosome 6 (149,504,495 to 149,546,092, reverse strand). Ensembl gene ENSG00000131013.
Subcellular location: Nucleus
Subcellular location (Human Protein Atlas): Nucleoplasm; Cytosol
Pathways (Reactome):
Disease: Dengue Virus-Host Interactions
Metabolism of RNA: mRNA Splicing - Major Pathway
Gene Ontology:
Molecular function: protein binding; RNA binding; nucleic acid binding; peptidyl-prolyl cis-trans isomerase activity
Biological process: mRNA splicing, via spliceosome
Cellular component: cytosol; nucleoplasm; spliceosomal complex; U2-type catalytic step 1 spliceosome; nucleus
Genetic constraint (gnomAD): Loss-of-function variants: 11 observed, 16.73 expected, observed/expected ratio (o/e) 0.66, 90% interval 0.41 to 1.09. The upper end of that interval is the gene's LOEUF score, 1.09, which puts it in group 4 of 6, group 1 being the genes least tolerant of losing a copy. Missense variants: 124 observed, 147.72 expected, observed/expected ratio (o/e) 0.84, 90% interval 0.73 to 0.97. Synonymous variants: 49 observed, 48.39 expected, observed/expected ratio (o/e) 1.01, 90% interval 0.8 to 1.28.
Homologues: Orthologues: chimpanzee PPIL4 (99% identical), macaque PPIL4 (99% identical), dog PPIL4 (98% identical), pig PPIL4 (98% identical), rat Ppil4 (98% identical), mouse Ppil4 (97% identical), guinea pig PPIL4 (97% identical), zebrafish ppil4 (68% identical), Drosophila melanogaster CG5808 (52% identical), Caenorhabditis elegans sig-7 (45% identical). Paralogues in human: NKTR (24% identical), PPIG (21% identical), PPID (17% identical), CWC27 (16% identical), PPIF (14% identical), PPIB (13% identical), PPIA (13% identical), PPIE (13% identical), PPIL2 (13% identical), PPIL3 (13% identical), PPIC (13% identical), PPIAL4C (12% identical), and 10 more.
Diseases named in the same sentence as PPIL4 in open-access papers:
PPIL4 is named in the same sentence as 1 disease in open-access papers, as found by Europe PMC text mining. Sharing a sentence is not in itself a finding about the gene and the disease.
PPIL4 shares sentences with these, for which no sentence is quoted: breast carcinoma (1 paper).